ARX (aristaless related homeobox)
Diseases named in the same sentence as ARX in open-access papers (continued):
Sharing a sentence is not in itself a finding about the gene and the disease.
infantile spasms (16 papers, 2005 to 2025). A rare epilepsy syndrome characterized by onset of epileptic spasms in infants between 2 and 12 months of age, and rarely up to 24 months. "ARX mutation-associated syndromes with brain malformations include the following X-linked polyA diseases: infantile epileptic-dyskinetic encephalopathy, infantile spasms, and Partington syndrome." (PMID 36169768, 2023). "Here, we present a 7-year-old boy with infantile spasm syndrome caused by a novel mutation of the ARX gene, as confirmed by exome sequencing." (PMID 32257294, 2020). "We report a 7-year-old boy with infantile spasms caused by a novel mutation in the Aristaless-related homeobox (ARX) gene." (PMID 32257294, 2020). "The pattern was identical to that observed for two samples known to have the dup24 mutation in exon 2 of ARX and clearly distinct from the 21 bp insertion in exon 2 that is present in the patient with West Syndrome." (PMID 15850492, 2005). "ARX mutation-associated infantile epileptic-dyskinetic encephalopathy is characterized by severe mental retardation, early-onset infantile spasms, and severe generalized dystonia that has a progressive course in the first years of life before reaching a plateau." (PMID 36169768, 2023). "PolyA expansion is found in the second polyA tract in ARX mutation-associated infantile spasms and Partington syndrome (X-linked mental retardation, seizures, and mild distal dystonia), and these diseases have not been associated with brain abnormalities on neuroimaging examinations." (PMID 36169768, 2023). "Variants in these patients and associated phenotypes are described as follow; two variants of SCN1A (c.1703G > A/p.R568Q, c.4176T > A/p.N1392K) were identified in two patients of unclassified EEES and one variant of ARX (c.1600G > C/p.A534P) in a West syndrome patient." (PMID 28387369, 2017). "Infantile Spasms Syndrome (ISS), the most common DEE, was one of the first linked to single-gene variants, including polyalanine expansions in the Aristaless Related Homeobox (ARX) gene." (PMID 41390005, 2025). "In terms of treatment, early developmental estradiol therapy can prevent ARX‐related infantile spasms and seizures by regulating downstream target genes of ARX." (PMID 36065764, 2022). "In conclusion, we identified a novel ARX mutation (c.1448 + 1 G > A) in a Japanese boy who presented with infantile spasm syndrome without severe brain malformation." (PMID 32257294, 2020). "Collectively, these findings suggest that PHF8 and ZNF711 may act as gene modifiers of ARX-disease phenotypes; thus, variants in these NDD genes may contribute to the phenotype variability from West syndrome to Partington syndrome to mild ID caused by ARX polyalanine expansions." (PMID 34356104, 2021). "ARX mutations are responsible for a rich spectrum of EIEE syndromes, for which phenotypic severity often correlates with the degree of structural damage to the protein, and include X-linked infantile spasms syndrome (ISSX), Ohtahara syndrome and severe dyskinetic disorders." (PMID 32033960, 2020).
autism (12 papers, 2005 to 2025). Persistent deficits in social interaction and communication and interaction as well as a markedly restricted repertoire of activity and interest as well as repetitive patterns of behavior. "Here, we report a female child with autism, global developmental delay, seizures, and brain malformation associated with a novel de novo frameshift variant of the ARX gene." (PMID 36845779, 2023). "This article describes the role of genetic testing using whole-exome sequencing (WES) in detecting a novel de novo frameshift variant in the ARX gene in a female patient with autism, seizure, and global developmental delay." (PMID 36845779, 2023). "We identified a novel de novo frameshift variant in the ARX gene using the WES approach in a female patient with autism, seizures, and global developmental delay phenotype." (PMID 36845779, 2023). "For example, ARX is required for normal telencephalic development and is associated with syndromic autism and other neurodevelopmental disorders, while EMX1 and FOXB1 also play important roles in neural development." (PMID 31893020, 2019). "Finally, perhaps the variants in DLX2, DLX5 and ARX, all of which alter the development of forebrain GABAergic neurons, are providing a clue that an increase in the ratio of excitation/inhibition underlies some forms of autism." (PMID 16266434, 2005). "Of note, many target genes of this pleiotropic TF have been correlated with ID and autism, emphasizing the importance of ARX for brain development and functioning." (PMID 35328505, 2022). "The SAE1 gene is involved in protein sumoylation process and is shown to interact with the ARX gene, which is involved in Autistic disorder." (PMID 23275889, 2012).
insulinomas (11 papers, 2020 to 2025). "It is worth noting that in another study, three metastatic insulinomas were included and exclusively displayed positivity for ARX (>10% of cells) and ALT, indicating that PDX1 and ARX expression are merely partially bound to hormonal activity." (PMID 39456803, 2024). "Previous studies have shown that non-metastatic insulinomas exclusively expresses PDX1, whereas liver metastatic foci and metastatic insulinoma are more likely to express ARX." (PMID 37251916, 2023). "It seems that the accumulated ARX expression was important for malignant signatures of metastatic insulinomas, but it needs further exploration." (PMID 37251916, 2023). "PDX1 expression was observed in 34/35 primary insulinomas (97%), and 2/3 liver metastases; in contrast, only 3/35 (9%) of primary insulinomas were ARX positive, while all liver metastases were ARX positive." (PMID 32103422, 2020). "Meanwhile, the accumulation of ARX expression may be involved in the progression of metastatic insulinomas." (PMID 37251916, 2023). "the liver metastasis showed ARX+ features resembling NF-PanNETs, indicating the accumulated ARX expression may play an important role in the progression of metastatic insulinomas." (PMID 37251916, 2023). "The preoperative elevated proinsulin levels and proinsulin/insulin molar ratio could predict the malignancy of insulinoma as well as ARX expression by IHC staining." (PMID 37251916, 2023). "Transdifferentiation of ARX-positive PNENs to insulin-producing PNENs could provide an explanation for these observations and the more malignant behavior of these exceptional insulinomas." (PMID 32512761, 2020). "Thus, strong ARX expression in more than 10% of cells identified metastatic insulinomas with a 100% sensitivity and specificity." (PMID 32103422, 2020). "All ARX positive primary insulinomas developed metastases during follow-up." (PMID 32103422, 2020). "Furthermore, we demonstrate that ARX—which is normally not present in beta-cells—is expressed in a subset of insulinomas and is associated with large tumor size, ALT, and metastatic disease." (PMID 32103422, 2020). "Of note, two insulinomas and the glucagonoma were ARX positive and PDX1 negative, as assessed by immunohistochemistry." (PMID 41212394, 2025). "Of interest, the aggressive insulinomas displayed aristaless-related homeobox (ARX) expression, which is usually absent in beta-cells and present in alpha cells, suggesting either dedifferentiation or an alpha cell-of-origin mechanism in these tumors." (PMID 39954168, 2025). "This strongly suggests distinct endocrine (de)differentiation in aggressive insulinomas versus small and indolent insulinomas, with similarities of aggressive insulinomas to non-functional PanNETs which often co-express ARX/PDX1." (PMID 39331358, 2024). "Of interest, whereas typical small insulinomas show strong PDX1 expression but no ARX expression (as seen in normal beta-cells), aggressive insulinomas also express ARX (lacking in normal beta-cells, but present in alpha- or gamma-cells)." (PMID 39331358, 2024). "For these four patients, the proinsulin/insulin molar ratio <1 and primary tumors were all present as PDX1+, ARX-, and insulin+, which were similar to non-metastatic insulinomas." (PMID 37251916, 2023). "PDX1 staining positive was commonly found in non-metastatic insulinomas, while ARX staining positive was preferred in a portion of NF-PanNETs." (PMID 37251916, 2023). "A portion of metastatic insulinomas were largely derived from non-metastatic insulinomas in hormone secretion and ARX/PDX1 expression patterns." (PMID 37251916, 2023). "The ARX transcription factor is not expected to be expressed in insulinomas, as it is not expressed in pancreatic beta-cells." (PMID 32103422, 2020). "As expected, the majority of insulinomas expressed PDX1, except one malignant and one DAXX/ATRX mutated insulinomas, which showed nuclear positivity for ARX but not for PDX1." (PMID 33288854, 2020).
insulinomas (continued). "We determined protein expression of ARX and PDX1 together with ATRX, DAXX, ARID1A, and H3K36me3 by immunohistochemistry, as well as ALT and CDKN2A deletions by fluorescence in situ hybridization (FISH), in a cohort of clinically defined sporadic insulinomas." (PMID 32103422, 2020). "Therefore, we determined ARX and PDX1 expression in a cohort of 35 sporadic primary insulinomas and two liver metastases of inoperable primary insulinomas." (PMID 32103422, 2020). "In contrast, ARX expression was absent in any of the small indolent insulinomas in this study or the previous literature." (PMID 32103422, 2020). "Rarely, metastatic insulinomas show ARX positivity with concurrent loss of DAXX/ATRX and ALT activation, suggesting a distinct tumorigenic mechanism in malignant insulinomas similar to nonfunctional pancreatic NETs through transdifferentiation from α cell tumors." (PMID 40026252, 2025). "The presence of ARX expression, which is usually absent in beta-cells, and genetic alterations not seen in indolent insulinomas strongly suggest a distinct tumorigenic mechanism in malignant insulinomas, with similarities to non-functional PanNETs." (PMID 32103422, 2020). "Out of the six insulinomas, four were positive for ARX and negative for PDX1, one was negative for ARX and positive for PDX1, and for one sample the immunohistochemistry was not available." (PMID 41212394, 2025). "Only for the intermediate-ADM insulinoma, data on PDX1 and ARX were available; it resulted positive for ARX, and negative for PDX1 expression." (PMID 33288854, 2020). "All three primary insulinomas that metastasized showed ARX expression, 2/3 showed ALT, and 1/3 had a homozygous deletion of CDKN2A as opposed to absence of ARX expression, ALT, or CDKN2A deletions in the 32 non-metastatic cases." (PMID 32103422, 2020). "Whether the ARX and PDX1 transcription factors play a role in the clinical behavior of insulinomas is not known." (PMID 32103422, 2020).
Partington syndrome (11 papers, 2014 to 2025). A rare neurological condition that is primarily characterized by mild to moderate intellectual disability and dystonia of the hands. "Fine mapping of the Partington syndrome locus, as well as identification of the causal ARX gene and ARXdup24 variant was accomplished in 2002." (PMID 41153441, 2025). "Other disorders that have been linked to ARX poly-alanine tract expansions include hydrocephaly with abnormal genitalia, myoclonic epilepsy with spasticity and mental retardation, Partington syndrome, and X-linked infantile spasms." (PMID 29186753, 2017). "ARX is associated with diseases including early infantile epileptic encephalopathy 1 (EIEE1) and Partington syndrome." (PMID 31104630, 2019).
Epileptic encephalopathy (8 papers, 2015 to 2024). A condition in which epileptiform abnormalities are believed to contribute to the progressive disturbance in cerebral function. "Ohtahara syndrome or Type 1 early infantile epileptic encephalopathy is a severe early‐onset epileptic encephalopathy with arrest of psychomotor development caused by hemizygous mutations in the ARX gene, which encodes a transcription factor in fundamental brain developmental processes." (PMID 38400608, 2024). "In the case of Patient 6, with ‘epileptic encephalopathy, early infantile, 4’ secondary to a mutation in the ARX gene, the known causal variant was not captured by the TruSight One panel, and was therefore not present in the genotype data for this individual." (PMID 29044180, 2017).
X-linked lissencephaly (7 papers, 2012 to 2025). "ARX, a gene important for mammalian germ cell development and associated with X-linked lissencephaly and testis dysgenesis, was also identified as a key differentially expressed TF in this dataset and localized to gonadal interstitial and OSE populations." (PMID 40328871, 2025). "Mutations in ARX have been linked to cases of X-linked lissencephaly with abnormal genitalia in humans." (PMID 36070311, 2022). "Humans with mutations in the transcription factor Aristaless Related Homeobox (ARX) often suffer from the syndrome X-linked lissencephaly with ambiguous genitalia (XLAG), affecting many cell types including those of the pancreas." (PMID 26633894, 2015). "Many genetic syndromes are associated with AgCC (e.g., X-linked lissencephaly, Mowat-Wilson syndrome, CRASH syndrome), and some of these syndromes have been associated with autism (i.e. ARX mutations leading to X-linked lissencephaly)." (PMID 23171505, 2012). "Humans with X-linked lissencephaly with ambiguous genitalia (XLAG, OMIM # 300215) represent some of the most severe clinical effects of null mutations in ARX through functional loss of the DNA binding prd-like homeodomain." (PMID 26633894, 2015).
developmental delay (6 papers, 2015 to 2024). "We describe worsening neuropsychiatric symptoms in the offspring of a Korean family with ID/developmental delay (DD) caused by a novel ARX p.Lys385Ter variant." (PMID 39408661, 2024). "A study examined the ARX gene mutation in a patient‐reported ambiguous genitalia and global developmental delay phenotypes with poor cognitive abilities." (PMID 38400608, 2024). "In the present study, a heterozygous ARX mutation has been found in a female IEE patient with multiple seizure types, spastic dystonic quadriplegia and severe developmental delay." (PMID 25951140, 2015).
Dystonia (6 papers, 2011 to 2023). An abnormally increased muscular tone that causes fixed abnormal postures. "A subset of FS symptoms, such as dystonia, myoclonus, and ataxia, may be attributed to the downregulation of PLEKHG2, DST, ARX, AAAS, KCTD17, PRDM8, and CRTC1 in FS brains as these genes are downregulated in Q84Pfs-Het brains and play a role in these movement and muscle coordination 43–49." (PMID 37398410, 2023).
microcephaly (6 papers, 2015 to 2023). A congenital or acquired developmental disorder in which the circumference of the head is smaller than normal for the person's age and sex. "What is the pathogenic mechanism for ARX mutations to result in microcephaly?" (PMID 38094004, 2023). "Interestingly, individuals with ARX variants can have either congenital or postnatal microcephaly." (PMID 38094004, 2023). "In this study, I focus on several homeobox genes (ARX, LHX2, MEIS2, NKX2-1, OTX1, OTX2, and PAX6) implicated in the pathogenesis of microcephaly." (PMID 38094004, 2023). "The brains of these mice are smaller, resembling the microcephaly observed in humans with an ARX mutation; however, these mice do not develop seizures." (PMID 38094004, 2023).
brain malformations (5 papers, 2014 to 2025). "Truncation mutations and missense mutations in the ARX homeodomain result in severe brain malformation phenotypes, while missense mutations outside of the homeodomain and expansion of the poly-alanine tracts are associated with non-malformation phenotypes." (PMID 38612920, 2024). "This duplication occurs in 67%-76% of all unrelated ARX mutated patients without brain malformation, considering the potential for ascertainment bias as the gene sequencing is not routinely available." (PMID 24528893, 2014). "The c.429_452dup24 of the ARX gene is a rare genetic anomaly, leading to X-Linked Intellectual Disability without brain malformation." (PMID 24528893, 2014). "The ARX-associated disorders may be divided into two categories based on presence or absence of brain malformations." (PMID 38612920, 2024).
X-linked intellectual disability (5 papers, 2011 to 2023). An X-linked intellectual deficiency in which not enough information is known, reported or published to indicate whether a gene causes non-syndromic or syndromic presentations. "The Aristaless Related homeoboX (ARX) is an important gene responsible for X-Linked Intellectual Disability (XLID) that belongs to the paired (Prd) class homeoprotein." (PMID 33757564, 2021).
Down syndrome (4 papers, 2014 to 2024). "Other than Down syndrome, the commonest known cause with a birth prevalence of ∼1/1,000 live births, other much rarer syndromes include Angelman, ARX, Coffin-Lowry syndrome, Cornelia de Lange, Fragile X, PCDH19, Prader–Willi, and Rett and Williams syndromes." (PMID 36090348, 2022). "We also included a group of 27 age- and IQ-matched Down syndrome patients who served as controls to ensure our data were not resulting from low-cognitive functioning, but were specific to the ARX gene mutation." (PMID 24528893, 2014).
Ohtahara syndrome (4 papers, 2015 to 2025). "Mutations in the aristaless-related homeobox gene are associated with early infantile epileptic encephalopathy (also known as Ohtahara syndrome) and other epileptic encephalopathies such as West syndrome and X-linked myoclonic epilepsy." (PMID 39976094, 2025). "EIEE1 (Ohtahara syndrome) is a rare X‐linked recessive disorder specified by acute early‐onset epileptic encephalopathy with the stop of psychomotor development, which arises from the mutations in the ARX gene." (PMID 38400608, 2024).
pancreatic neuroendocrine tumor (4 papers, 2020 to 2026). Pancreatic endocrine tumor, also known as pancreatic neuroendocrine tumor (PNET), describes a group of endocrine tumors originating in the pancreas that are usually indolent and benign, but may have the potential to be malignant. "The transcription factors ARX and PDX1, and alternative lengthening of telomeres (ALT) were recently described as prognostic markers for resected non‐functional pancreatic neuroendocrine tumors (PanNETs)." (PMID 31846235, 2020).